MTOR (mechanistic target of rapamycin kinase)
Diseases named in the same sentence as MTOR in open-access papers (continued):
Sharing a sentence is not in itself a finding about the gene and the disease.
Hypertension (continued). "Specifically, hypertension, higher calcineurin, use of mTOR inhibitors, higher dose of mycophenolate, as well as lower absolute B-cell counts contributed to low response, while higher CD19+ B cell counts were associated with sero-response." (PMID 41235244, 2025). "We believe that a deeper understanding of the mTOR pathway in GD cases is necessary, especially regarding the immunophenotypic profile of more complex cases, which often involve a GD patient with hypertension or late-onset PE." (PMID 41226334, 2025). "The main aim of this narrative review is to present the mechanism by which mTOR can induce the development of IR and, further, of hypertension." (PMID 39200267, 2024). "miR‐193b‐3p and miR‐346 were found to be involved in the neurogenic pathogenesis of hypertension from different aspects, such as negative regulation of intrinsic apoptotic signaling pathway (GO: 2001243) and mTOR signaling pathway." (PMID 38934856, 2024). "More precisely, reduced mTOR activity in juvenile SHRs can disrupt sodium balance, leading to fluid retention and volume-dependent hypertension in mature animals." (PMID 39513878, 2024). "The findings, such as regulation of autophagy of mitochondrion (GO: 1903146), Mammalian target of rapamycin (mTOR) signaling pathway, cAMP signaling pathway, and calcium signaling pathway, were also reflected in the neurogenic pathogenesis of hypertension." (PMID 38934856, 2024). "AMP‐dependent protein kinase/mammalian target of rapamycin (AMPK/mTOR) signalling pathway are involved in hypertension‐induced autophagy." (PMID 38712979, 2024). "Increased salt intake activates the RAAS system and further PI3K/AKT/mTOR, leading to NO decreased production and hypertension development." (PMID 39200267, 2024). "Taking into consideration all these aspects, mTOR overactivation plays a pivotal role in IR and hypertension pathology." (PMID 39200267, 2024). "These vascular alterations were impacted by levels of PI3K/Akt/mTor signaling, and several case reports have reported vascular abnormalities, namely hypertension, in some NKH patients." (PMID 36551976, 2022). "This promising anti-hypertensive profile has led to the consideration of mTOR inhibitors as a primary therapy for specialized difficult-to-treat populations with hypertension including pulmonary arterial hypertension and primary hyperaldosteronism." (PMID 36211586, 2022). "The mTOR pathway was also reported to be the most important DEG-enriched pathway in severe OSA patients with hypertension." (PMID 36468038, 2022). "Combined with the prediction of the PI3K–Akt signal pathway, AGE–RAGE signal pathway, and mTOR signal pathway were closely related to the vascular remodeling of hypertension treated by PGQYD." (PMID 33568194, 2021). "Analysis of PBMCs using the Kyoto Encyclopedia of Genes and Genomes database showed that the mTOR signaling pathway (P=0.006) was the most important differential gene-enriched pathway in severe-OSA patients with hypertension." (PMID 34888100, 2021). "We have recently found that mTOR (mammalian target of rapamycin) related mechanisms are importantly involved in the regulation of Na+ homeostasis and salt-induced hypertension in SS rats." (PMID 33790341, 2021). "Over the past years, strong evidence has suggested that the mammalian target of rapamyoin (mTOR) overactivation plays important roles in the fibrosis process, and suppressing mTOR is a target for preventing hypertension and its related fibrosis." (PMID 33117428, 2020). "In all patients and those treated with TK/VEGF- and mTOR-directed 1 L treatment, the three most common AEs were hypertension, nausea/vomiting and renal insufficiency." (PMID 31174493, 2019). "Doxazosin, an hypertension drug was shown to decrease VEGFR-2/Akt/mTOR signalling and to exert antitumor effects in an animal model." (PMID 25825981, 2015).
Hypertension (continued). "Our search identified six studies (all conversion) that measured hypertension in liver transplant recipients receiving mTOR inhibitors." (PMID 24719752, 2014). "In Phase III trials evaluating VEGF and mTOR inhibitors, the most common grade 3 and 4 AEs observed including hypertension, decreased left ventricular ejection fraction, hand-foot-syndrome and myelosuppression." (PMID 22123271, 2011). "In the immune response to hypertension, inhibiting the mTOR signaling pathway promotes Treg polarization and suppresses Th17 differentiation, which may help alleviate immune-mediated inflammation in hypertension." (PMID 40513070, 2025). "Additionally, reduced mTOR elevates oxidative stress, promotes fibrosis, and weakens autophagy, worsening kidney function and contributing to hypertension." (PMID 39513878, 2024). "Lactobacillus rhamnosus can regulate the levels of intestinal metabolites and CD4+ T-cell-induced inflammation through mTOR, thereby alleviating hypertension development and suggesting a correlation between the gut microbiome and mTOR immune balance in hypertension." (PMID 34888100, 2021). "Sixty one percent of the kidney transplant recipients were male, and most of them had arterial hypertension (91%) and received non-mTOR-inhibitor based regimen (64%) (mainly tacrolimus-mycophenolic acid) and 36% an mTOR-inhibitor based regimen (sirolimus or everolimus)." (PMID 33917093, 2021). "The activation of the mTOR signaling pathway is thought to be closely related to hypertension." (PMID 34888100, 2021). "Moreover, probiotics regulating immune balance via the mTOR signaling pathway are effective in treating hypertension." (PMID 34888100, 2021). "Pre-emptive intervention for renal angiomyolipomas with embolisation, surgery, or mammalian target of rapamycin (mTOR) inhibitor may have abolished the gender difference in impaired renal function, hypertension, and other complications." (PMID 33041968, 2020). "Inhibition of mTOR pathway almost reversed these effects, suggesting that ketone body might contribute to cardiac fibroblasts via mTOR pathway in hypertension." (PMID 33117428, 2020). "Conventional cancer chemotherapy treatments such as vinca alkaloids, platinum compounds, taxanes, as well as serine-threonine kinase mammalian target-of-rapamycin (mTOR) inhibitors, and head and neck cervical radiotherapy are all recognized hypertension precipitants." (PMID 33081013, 2020). "Maybe patients prone to develop severe hypertension could benefit from antihypertensive therapy prior to the start of a treatment with multikinase and mTOR inhibitors." (PMID 28796163, 2017). "The pathogenesis of hypertension caused by inhibitors of the VEGF and mTOR signaling pathways may offer selective targets of antihypertensive treatment in the future." (PMID 28796163, 2017). "However, p70SK6 phosphorylation was dramatically elevated in LV of hypertensive animals suggesting activation of mTOR, and providing further support for a reduced autophagic state in LV during hypertension." (PMID 25799101, 2015). "The mTOR pathway is not only essential for immune response regulation but also for the differentiation and activation of T-cells, B-cells, and myeloid cells, underscoring its importance in maintaining immune balance and its potential influence on hypertension development." (PMID 39513878, 2024). "Therefore, suppressing the AMPK/mTOR signalling pathway may mitigate hypertension‐induced cardiomyocyte autophagy." (PMID 38712979, 2024). "Under pathological settings, such as hypertension, the heart deals with sustained, chronic levels of mechanical strain and this can lead to persistent activation of protein synthesis pathways such as mammalian target of rapamycin (mTOR) which regulate cardiomyocyte growth." (PMID 32083081, 2020).
Hypertension (continued). "Whether the net effect of multikinase/mTOR inhibitor therapy versus manifest arterial hypertension favors the anticancer therapy depends mainly on the severity of hypertension and the effect of antihypertensive treatment and needs to be assessed clinically for each individual patient." (PMID 28796163, 2017). "Treatment with Lactobacillus rhamnosus GG prevents increases in BP in rat models of OSA-induced hypertension by lowering TMAO and rebalancing Th1/Th2 cytokines and by modulating the PI3K/Akt/mTOR signaling pathway." (PMID 37107242, 2023). "Secondly, the study population was small and heterogeneous in terms of age, presence of arterial hypertension, the extent of renal involvement, genetic background (TSC1, TSC2, TSC2+PKD1), and treatment with mTOR inhibitors." (PMID 34912759, 2021). "In the present study, we show that TMZ is able to reverse SU-induced hypertension and LVD, with the involvement of AMPK/mTOR/autophagy pathway in cardiomyocytes." (PMID 31545912, 2019). "Hypertension due to treatment of RCC with multikinase and mTOR inhibitors differs from other forms of hypertension in many ways." (PMID 28796163, 2017). "Hypertension as an AE of combined VEGF kinase and mTOR inhibition is mainly due to VEGF kinase inhibition." (PMID 28796163, 2017). "The link between mTOR dysregulation, IR, hypertension and mTOR inhibitors has not been fully described." (PMID 39200267, 2024). "Hypertension is a frequent and severe AE, when VEGF inhibitors are applied as an antiangiogenic agent, whereas it is less frequent and less severe with mTOR inhibition." (PMID 28796163, 2017). "Hypertension occurs in 17–45 % of TKI-treated patients (40 % pazopanib, 30 % sunitinib, 4–11 % sorafenib) and bevacizumab (3–11 %) patients, but is rarely described with mTOR inhibitors." (PMID 26906039, 2016). "Interestingly, upregulation of AMPK has also been observed in the LV in hypertension; however, no inhibition of mTOR and p70s6K was observed in the LV of the hypertensive rat." (PMID 28340591, 2017). "Future research is required to elucidate whether it is possible to design new multikinase/mTOR or other signaling pathway inhibitors that can improve PFS and OS in mRCC without causing arterial hypertension and other AE associated with increased morbidity and mortality." (PMID 28796163, 2017).
pancreatic neuroendocrine tumor (83 papers, 2011 to 2026). Pancreatic endocrine tumor, also known as pancreatic neuroendocrine tumor (PNET), describes a group of endocrine tumors originating in the pancreas that are usually indolent and benign, but may have the potential to be malignant. "The third relevant cluster of commonly mutated genes are alterations in genes belonging to the mTOR pathway, which are mutated in about 15% of the pancreatic NET, mostly affecting PTEN, TSC1, and TSC2." (PMID 34647171, 2022). "Mutations in genes of mTOR pathway were reported in 14% of pancreatic neuroendocrine tumors (p-NETs)." (PMID 32373532, 2020). "Loss of function of TSC1 and TSC2 leads to mTOR activation in patients with tuberous sclerosis, which has been associated with pancreatic NETs." (PMID 25092520, 2014). "Second, whole exome sequencing analysis of sporadic pancreatic NETs has identified somatic mutations in genes involved in the mTOR pathway, including PTEN, TS2, and PIK3CA, in 15 % of cases [24•]." (PMID 25092520, 2014). "In a randomized, placebo-controlled study of patients with advanced pancreatic NET, treatment with the mTOR inhibitor everolimus was associated with improved progression-free survival (PFS)." (PMID 25092520, 2014). "Activation of the mTOR pathway has also been implicated in the proliferation of pancreatic neuroendocrine tumors." (PMID 24133453, 2013). "Moreover, PI3K/AKT/mTOR signaling is a major pathway implicated in the pathogenesis of well-differentiated pancreatic neuroendocrine tumors." (PMID 34247193, 2021). "Furthermore, genetic profiling is becoming more and more important for treatment choices; for instance with the choice for a targeted therapy, such as mTOR inhibitors in pancreatic neuroendocrine tumors or PARP inhibitors in BRCA deficient tumors." (PMID 27267993, 2016). "Genomic studies focusing on pancreatic NETs highlighted mutations in MEN1, DAXX, ATRX, and targets in mTOR pathway." (PMID 41483302, 2026). "Pancreatic neuroendocrine tumors (PanNETs) lack metabolic zonation due to dense vascularization, showing homogeneous glycolytic phenotypes throughout via aberrant mammalian target of rapamycin (mTOR)-vascular endothelial growth factor (VEGF) crosstalk." (PMID 40725147, 2025). "Based on prior data, the most prevalent mutations in pancreatic neuroendocrine tumors include those in MEN1 (44%), DAXX/ATRX (43%) 17, 18, and genes related to the mTOR pathway." (PMID 41323792, 2025). "Everolimus, a mammalian target of rapamycin inhibitor, has shown efficacy in treating pancreatic neuroendocrine tumors, including insulinomas, by inhibiting the mammalian target of rapamycin (mTOR) pathway." (PMID 39723310, 2024). "And the mammalian target of rapamycin (mTOR) kinase pathway was identified in human pancreatic neuroendocrine tumor cell lines." (PMID 37940761, 2024). "Everolimus, an oral inhibitor of the mammalian target of rapamycin (mTOR), and sunitinib, a multi-targeted tyrosine kinase inhibitor, have both shown promising results in pancreatic NETs." (PMID 38817893, 2024). "Mutations of genes of the mTOR pathway, such as PTEN, TSC2 and PIK3CA, have been detected in about 16% of sporadic pancreatic NETs." (PMID 39199391, 2024). "They found four signaling pathways including DNA damage repair, chromatin modification, altered telomere length and mTOR signaling, which were involved in the occurrence and development of pancreatic NETs." (PMID 37387515, 2023). "Chemotherapy and mammalian target of rapamycin (mTOR) or tyrosine kinase inhibitors (TKI) were significantly more often used in patients with pancreatic NETs (p-value p < 0.001)." (PMID 36765740, 2023).
pancreatic neuroendocrine tumor (continued). "The allosteric mTOR inhibitor everolimus was approved by FDA for pancreatic NET treatment, thanks to its ability to target mTOR complex 1 (mTORC1) and its anti-proliferative and anti-angiogenic properties." (PMID 36835022, 2023). "In the context of malignant transformation from islet cells to pancreatic neuroendocrine tumors (PanNETs), there is often overexpression of AKT and the presence of mutations in the AKT/mTOR pathway." (PMID 38030709, 2023). "The RADIANT-3 trial, for instance, showed an improved progression-free survival (PFS) of 11 months for patients suffering from advanced, progressive pancreatic NETs (pNETs) treated with the mTOR inhibitor everolimus compared to 4.6 months for placebo." (PMID 36551858, 2022). "MEN1 is known to interact with genes of chromatin modifications, altered telomere length, DNA damage repair, and mTOR signaling, which are the four main genetic pathways involved in the development of pancreatic NETs." (PMID 34647171, 2022). "Targeted therapies including the mTOR inhibitor everolimus and multikinase inhibitor sunitinib were approved for progressive pancreatic NET." (PMID 35428913, 2022). "Subsequently, patients with pancreatic NETs were treated with the mTOR inhibitor everolimus in a large clinical trial, in which patients with ileal NETs were also included." (PMID 34680217, 2021). "On the other hand, while dual PI3K and mTOR inhibitor showed improved efficacy in inhibiting tumor growth in preclinical models, adverse effects and poor tolerability were also reported for pancreatic neuroendocrine tumors patients." (PMID 34304249, 2021). "Enforced serine/threonine kinase 33 expression promotes the growth of pancreatic neuroendocrine tumor via activating PI3K/Akt/mTOR pathway." (PMID 32969473, 2020). "In particular, targeting the PI3K/AKT/mTOR pathways using mTOR inhibitors improved progression-free survival in patients with advanced pancreatic neuroendocrine tumors." (PMID 30701022, 2018). "mTOR pathway activation and hypervascularity have been identified as important characteristics of pancreatic neuroendocrine tumors (pNETs)." (PMID 29262588, 2017). "The mammalian target of rapamycin (mTOR) inhibitor everolimus recently obtained approval from the Food and Drug Administration for the treatment of patients with advanced pancreatic neuroendocrine tumors (pNETs)." (PMID 28454119, 2017). "TS has been associated with pancreatic NETs, and the loss of the TSC1/2 genes similarly leads to activation of mTOR signaling." (PMID 29255447, 2017). "The mammalian target of rapamycin (mTOR) is a protein downstream in PI3K pathway, and its gene is mutated in 15% of pancreatic NETs (pNETs)." (PMID 29213282, 2017). "Recent genetic studies have highlighted that alterations in MEN1, chromatin remodeling genes, and mammalian target of rapamycin (mTOR) pathway genes are the most frequent molecular events identified in pancreas neuroendocrine tumors (pNETs)." (PMID 29212165, 2017). "Recent therapeutic advances with everolimus, a mammalian target of rapamycin (mTOR) inhibitor, and sunitinib, a multitargeted agent with antiangiogenic activity, have led to an improvement in patients with advanced pancreatic NETs (pNETs)." (PMID 26138480, 2015). "The mTOR inhibitor everolimus has been shown to significantly delay disease progression in patients with pancreatic NET." (PMID 25092520, 2014). "Recent studies have demonstrated that phosphatidylinositol-3-kinase(PI3K)-Akt/ mammalian target of rapamycin (mTOR) pathway is also involved in Pancreatic endocrine tumors (PETs) tumorigenesis and progression, cell survival, cell adhesion and metastasis." (PMID 24505326, 2014). "Recently, a trial with the mTOR inhibitor everolimus demonstrated efficacy in pancreatic NET, driven mainly by stable disease." (PMID 25327558, 2014).